ADAMTS13 (ADAM metallopeptidase with thrombospondin type 1 motif 13)
Diseases named in the same sentence as ADAMTS13 in open-access papers (continued):
Sharing a sentence is not in itself a finding about the gene and the disease.
Thrombocytopenia (154 papers, 2009 to 2026). A reduction in the number of circulating thrombocytes. "In larvae, ADAMTS13 loss unveiled a prothrombotic response to vascular injury, a phenotype masked in patients by thrombocytopenia." (PMID 41051174, 2025). "TTP is a rare but fatal condition characterized by microangiopathic anemia and thrombocytopenia largely due to the deficiency or decreased activity of ADAMTS13." (PMID 40296018, 2025). "Previous work in zebrafish showed that ADAMTS13 deficiency reproduces cTTP hallmarks, including thrombocytopenia, erythrocyte fragmentation, and spontaneous bleeding." (PMID 41051174, 2025). "Plasma exchange has been used to manage thrombocytopenia associated with low ADAMTS13 in septic patients." (PMID 39857914, 2025). "The presence of these autoreactive antibodies, and the ADAMTS13 depletion they cause, explain the benefit of medications that treat the resulting peripheral thrombocytopenia." (PMID 38540234, 2024). "The improved survival was associated with a greater recovery from thrombocytopenia, higher plasma ADAMTS-13 activity, and less thrombotic vascular occlusion." (PMID 37511541, 2023). "TTP was diagnosed if, in addition to microangiopathic hemolytic anemia and thrombocytopenia, ischemic organ involvement and severe deficiency in ADAMTS13 activity were present." (PMID 37762692, 2023). "More severe thrombocytopenia is likely to explain the higher prevalence of bleeding observed in patients with severe ADAMTS13 activity deficiency." (PMID 35739601, 2022). "The functional decrease in ADAMTS13 or incremental decline in ADAMTS13 activity in sepsis has been postulated to cause excessive platelet activation and thrombocytopenia in sepsis and ARDS." (PMID 35949449, 2022). "TTP is caused by a deficiency of ADAMTS13 leading to intravascular clotting causing thrombocytopenia and microangiopathic hemolytic anemia." (PMID 34667692, 2021). "It is characterized by microangiopathic hemolytic anemia and thrombocytopenia with the development of microthrombi caused by inherited or acquired deficiency of the von Willebrand factor-cleaving protease ADAMTS13 and resulting end-organ damage." (PMID 34552799, 2021). "For example, TTP is characterized by loss of ADAMTS13 function, thrombocytopenia, and schistocytosis." (PMID 35087853, 2021). "A 12-year-old boy with a history of intermittent thrombocytopenia in the prior 6 years had severe deficiency of plasma ADAMTS13 and harbored a novel compound heterozygous mutation which was also identified in his sister." (PMID 33014938, 2020). "Mutations in the ADAMTS13 gene family have been reported to cause congenital thrombotic thrombocytopenic purpura (cTTP), a rare disease characterized by thrombocytopenia and hemolytic anemia." (PMID 32197596, 2020). "Some studies have identified that a subgroup of SLE-associated TMA patients with acquired ADAMTS13 deficiency had a relatively benign outcome, even though these patients presented with extreme thrombocytopenia and CNS symptoms." (PMID 33374384, 2020). "Congenital TTP is due to ADAMTS13 gene mutation (Upshaw–Schulman syndrome) that usually presents with severe jaundice and thrombocytopenia in the neonatal period." (PMID 30223886, 2018). "Our results revealed that majority of the septic patients with thrombocytopenia were in the ADAMTS-13 deficient group." (PMID 23537039, 2013). "It has also been reported that deficiency of ADAMTS-13 plays an important role in sepsis-associated thrombocytopenia, which is seen in more than 50% of patients with sepsis and correlates with poor prognosis in these patients." (PMID 23537039, 2013). "Severe ADAMTS13 deficiency was reported in 33% to 90% of patients with TTP, whereas ADAMTS13 activity was found usually normal or slightly reduced in patients with HUS or other causes of thrombocytopenia." (PMID 20436664, 2010).
Thrombocytopenia (continued). "Among patients with severe thrombocytopenia and hemolytic anemia of unknown cause, the reduction in ADAMTS13 levels to <10% of normal values confirms a diagnosis of TTP." (PMID 37240470, 2023). "Elevating creatinine levels, signifying AKI, thrombocytopenia, and anemia in the setting of pancreatitis should raise the suspicion of aHUS, requiring further diagnostic workup such as peripheral blood smear and ADAMTS13 levels." (PMID 32481360, 2020). "Acquired TTP is associated with decreased metalloprotease ADAMTS-13 activity, which is a protease responsible for cleaving von Willebrand factor (vWF) multimers; failure to degrade vWF results in platelet aggregation and subsequent thrombocytopenia." (PMID 24649385, 2014). "Furthermore, we correlated ADAMTS-13 deficiency with sepsis associated thrombocytopenia and in-hospital mortality." (PMID 23537039, 2013). "We conclude that majority of the patients with severe sepsis have ADAMTS-13 deficiency that might also play a role in sepsis-induced thrombocytopenia." (PMID 23537039, 2013). "Finally, a case of dengue-associated microangiopathic thrombocytopenia due to an inhibitor of ADAMTS-13 was recently reported." (PMID 22563509, 2012). "Mutations in ADAMTS13 can be homozygous or compound heterozygous, which can result in either reduced production or increased clearance of the enzyme, leading to severe deficiency, an inability to cleave UL vWF multimers, platelet hyperaggregation, and consumptive thrombocytopenia." (PMID 40426866, 2025). "The association between clinical severity and endothelial activation, ADAMTS13 deficiency, thrombocytopenia, and impaired microvascular function suggests that thrombotic microangiopathy, systemic inflammation and microvascular dysfunction may contribute to pathogenesis of disease in vivax malaria." (PMID 25569250, 2015). "ADAMTS-13 deficiency might play a role in sepsis-induced thrombocytopenia." (PMID 23537039, 2013). "Frequent thrombophilia-related variants occurred in F5, SERPINC1, MTHFR, and FII, and inherited thrombocytopenias were linked to MPL, ANKRD26, THPO, DIAPH1, and ADAMTS13." (PMID 41929524, 2026). "TAMOF is associated with low ADAMTS13 activity, organ failure, acute kidney injury (AKI), and thrombocytopenia." (PMID 39857914, 2025). "The patient’s presentation of petechiae, thrombocytopenia, microangiopathic hemolytic anemia, elevated LDH, and indirect hyperbilirubinemia supported a diagnosis of TTP, typically caused by severe ADAMTS13 deficiency." (PMID 40821327, 2025). "Key laboratory indicators for both disorders include significantly elevated LDH, severe thrombocytopenia, declining Hgb, and the presence of schistocytes, with ADAMTS13 activity of <10% being specific to aTTP." (PMID 40242194, 2025). "Their pregnancies were complicated by thrombocytopenia, with many resulting in stillbirth or premature birth, emphasizing the need for ADAMTS13 activity testing in childhood and during pregnancy-associated thrombocytopenia." (PMID 40426866, 2025). "With new-onset thrombocytopenia (lowest platelet count was 38), an ADAMTS13 screen was ordered and returned positive." (PMID 40109809, 2025). "Although the clinical signs of TTP, such as fever, impaired consciousness, hemolytic anemia, and thrombocytopenia, improved after the initiation of treatment, the ADAMTS13 inhibitor persisted, and ADAMTS13 activity remained suppressed." (PMID 40091942, 2025). "In this case, the diagnosis was confirmed by the presence of severe thrombocytopenia, schistocytes, and markedly low ADAMTS13 activity." (PMID 41466911, 2025). "In patients with reduced ADAMTS13 activity and aPL, ADAMTS13 activity should be monitored, and the clinician has to check for thrombocytopenia and hemolytic anemia, the presence of schistozytes, and other clinical and laboratory parameters to discard TMA." (PMID 40283621, 2025).
Thrombocytopenia (continued). "Given the atypical clinical manifestations of cTTP, it is necessary to conduct ADAMTS13 activity and even genetic testing in patients with recurrent thrombocytopenia and end-organ damage." (PMID 39845832, 2024). "Relapse is defined as a new TTP episode with thrombocytopenia, microangiopathic anemia, and low ADAMTS13 activity 30 days or more after treatment completion." (PMID 39125707, 2024). "ADAMTS13 test returned to be normal and concurrent aHUS was eventually suspected, 26 days after the initial thrombocytopenia was presented." (PMID 38745129, 2024). "Thrombocytopenia seems to balance the increase in platelet aggregation that results from the increase in vWF and the decrease in ADAMTS13 activity." (PMID 39458229, 2024). "The removal of ADAMTS13 by antibodies to the enzyme appears to represent the best-known pathologic mediator leading to the observed thrombocytopenia that characterizes iTTP." (PMID 38540234, 2024). "ADAMTS‐13 activity levels of >10% make the diagnosis of TTP unlikely in patients presenting with acute thrombocytopenia." (PMID 36694637, 2023). "The patient was admitted to the pediatric intensive care unit with microangiopathic hemolytic anemia, severe thrombocytopenia, low von Willebrand factor-cleaving protease (ADAMTS13) activity, hypofibrinogenemia, gross hematuria, and acute kidney injury." (PMID 38192908, 2023). "All of them were characterized by microangiopathic hemolytic anemia, severe thrombocytopenia (<30 × 109/L) and ADAMTS13 activity of less than 5%." (PMID 38068357, 2023). "She demonstrated a rapid response to therapies, with resolution of anemia and thrombocytopenia within 1 week and normalization of ADAMTS13 activity within 2 weeks and resolving hemolysis over the following weeks." (PMID 35479064, 2022). "The diagnosis of secondary autoimmune TTP is possible in the presence of microangiopathic hemolytic anemia, thrombocytopenia, ADAMTS13 activity <10%, and demonstration of an anti-ADAMTS13 inhibitor." (PMID 35746657, 2022). "Severe thrombocytopenia at presentation was rare, with only one patient having a platelet count of 1 k/μL and an ADAMTS13 activity level of 118%." (PMID 33709050, 2021). "The clinical diagnosis of TTP is based on thrombocytopenia, microangiopathic hemolytic anemia and is confirmed by a disintegrin-like and metalloproteinase with thrombospondin type one motif, member 13 (ADAMTS13) <10%." (PMID 33842174, 2021). "This deficiency of ADAMTS13 was associated with both high vWF:Ag and ULVWF concentrations as well as with thrombocytopenia and increased LDH concentrations." (PMID 32122366, 2020). "The clinical relevance of reduced ADAMTS13 is well known from a disease termed TTP in which the formation of ULVWF multimers due to reduced ADAMTS13 leads to thrombocytopenia, hemolysis, AKI, and (often severe) neurological symptoms." (PMID 32122366, 2020). "Thrombocytopenia, DIC, and decreased ADAMTS-13 activity have all been associated with poor outcomes in sepsis." (PMID 32831133, 2020). "This thrombocytopenia is compensated, however, by elevated levels of adhesive protein vWF and decreased ADAMTS-13." (PMID 33425821, 2020). "This was further supported by low serum levels of ADAMTS13 prior to plasmapheresis and an improvement in clinical status, hemolytic anemia parameters, and thrombocytopenia shortly after plasma exchange therapy." (PMID 31228952, 2019). "Von Willebrand factor multimers are prothrombotic, thus ADAMTS13 inhibition leads to microthrombi formation, microangiopathic hemolytic anemia, thrombocytopenia and multiple organ injury, including renal injury." (PMID 30073173, 2018). "Deficiencies of ADAMTS13 results in the accumulation of VWF in the circulation and, consequently, thrombocytopenia." (PMID 28296884, 2017). "Regarding his thrombocytopenia, ADAMTS13 activity was found to be less than 10% and the positivity of anti-ADAMTS13 autoantibodies confirmed the diagnosis of associated autoimmune TTP." (PMID 28727752, 2017).
Thrombocytopenia (continued). "Thrombocytopenia persisted for 48 h in Adamts13+/+ mice injected with 13B4 & 14H7 (321 ± 65 x 103 platelets/μL) and recovered 4 days after the injection with rVWF." (PMID 27479501, 2016). "We assessed the incidence of TTP based on ADAMTS-13 activity in all consecutive pregnant or post-partum women presenting with thrombocytopenia less than 75 G/L." (PMID 26081109, 2015). "In cases of uncertain aetiology of thrombocytopenia, ADAMTS-13 activity was assessed by the full length technique." (PMID 26081109, 2015). "Activity of the VWF-cleaving-protease, ADAMTS13, was deficient in proportion to endothelial activation, IL-6, thrombocytopenia and vivax disease-severity, and associated with impaired microvascular reactivity in severe disease." (PMID 25569250, 2015). "Measurements of vWF and ADAMTS13 concentrations and activity would have defined the extent of this pathway’s contribution to the pathogenesis of thrombocytopenia." (PMID 25907925, 2015). "Thrombocytopenia due to abnormal platelet aggregation is usually recognized in patients with high VWF/ADAMTS13 ratio." (PMID 25960882, 2014). "Due to the combination of MAHA, thrombocytopenia, neurological symptoms, and decreased ADAMTS13 activity, our patient most closely fit the definition of TTP." (PMID 25429351, 2014). "In patients with severe sepsis and severe malaria, a similar imbalance in VWF and ADAMTS-13 was found and this was considered to be related to thrombocytopenia and organ dysfunction." (PMID 22563509, 2012). "High circulating levels of VWF in its active conformation, together with low ADAMTS-13 activity levels, are likely to contribute to the thrombocytopenia and complications of dengue." (PMID 22563509, 2012). "Case 1: a 10-year-old girl with recurrent anemia and thrombocytopenia since early childhood was found to have severe ADAMTS13 deficiency (<3%) without inhibitor." (PMID 41458739, 2025). "This condition is characterized by microangiopathic hemolytic anemia and thrombocytopenia, which can result from either an acquired deficiency of the ADAM metallopeptidase with thrombospondin type 1 motif 13 (ADAMTS13) or through complement-mediated mechanisms." (PMID 41466911, 2025). "Thrombotic thrombocytopenia purpura (TTP), defined clinically by microangiopathic hemolytic anemia and thrombocytopenia, is attributed to either inherited or acquired loss of VWF multimer size regulation caused by severe ADAMTS13 deficiency, resulting in the accumulation of UL–VWF multimers." (PMID 38473925, 2024). "Relapse was declared when, during a clinical remission, initial symptoms such as anemia or thrombocytopenia occurred, as well as in presence of abrupt or slowly progressive worsening of clinical status, or insidious alterations in laboratory values (i.e., ADAMTS13 activity < 10%)." (PMID 38068357, 2023). "Additionally, the presented case underscores the importance of ADAMTS13 testing in patients with hepatitis and thrombocytopenia." (PMID 37424014, 2023). "r-ADAMTS13 prevented severe thrombocytopenia and microthrombi in systemic tissues." (PMID 37240470, 2023). "There was thrombocytopenia and moderately low ADAMTS13 activity suggestive of TTP." (PMID 36065409, 2022). "There was no explicit diagnosis of thrombocytopenia-associated multiorgan failure (TAMOF) or ADAMTS13 levels checked." (PMID 36683785, 2022). "In contrast, PedSep-D had the most profound inflammatory response with highest M-CSF, IL-8, SCF, sCD163, IL-16, IL-10, TNF, and MIP1α levels, and thrombotic microangiopathic response with lowest ADAMTS13 activity decreased to < 57% of control with thrombocytopenia." (PMID 35526000, 2022). "Similarly, administration of inhibitory monoclonal antibodies against human recombinant ADAMTS13, target antigen in TTP, resulted in reduced ADAMTS13 activity, severe thrombocytopenia and hemolytic anemia in baboons." (PMID 35401530, 2022).
Thrombocytopenia (continued). "Also, treatment of mice with anti-ADAMTS13 single-chain variable-region fragments generated fatal thrombocytopenia." (PMID 35401530, 2022). "The role of platelet aggregation was supported by the finding that individuals with severe P. falciparum malaria deficient in a disintegrin and metalloprotease with thrombospondin type I repeats, member 13 (ADAMTS13), had higher frequencies of severe thrombocytopenia and other complications." (PMID 34943190, 2021). "All patients showed laboratory manifestations of MAHA including low Hb, PB, schistocytes >2%, increased reticulocytes, reduced haptoglobin, increased LDH, and thrombocytopenia, in addition to impaired renal function tests, and all of them had normal ADAMTS13 levels." (PMID 34840826, 2021). "Patients with thrombocytopenia, microangiopathic hemolysis, neurological symptoms, fever, and renal impairment may be tested for von Willebr and factor (vWF)- cleaving protease(ADAMTS13) activity and ADAMTS13 inhibitors." (PMID 32241296, 2020). "The screening TMA diagnosis was made according the following criteria: hemolytic anemia, thrombocytopenia and acute renal damage and without ADAMTS13 deficiency." (PMID 30388144, 2018). "It is essential to determine the ADAMTS13 activity in patients with thrombocytopenia with an unknown etiology." (PMID 29357939, 2018). "In patients with cirrhosis and thrombocytopenia, maintenance of normal primary hemostasis seems to depend greatly on concomitantly increased vWF levels and reduced levels of the vWF cleaving protease ADAMTS13." (PMID 25397410, 2014). "In conclusion, our data show that WPB exocytosis of VWF in its active conformation and consumption of VWF and ADAMTS-13 are prominent phenomena in severe dengue, which may contribute to thrombocytopenia and organ dysfunction." (PMID 22563509, 2012). "The lack of renal failure and significant thrombocytopenia or hemolytic anemia in vivax-associated coma does not suggest a thrombotic thrombocytopenic purpura-like syndrome due to altered vWF/ADAMTS13." (PMID 21666785, 2011). "ADAMTS13-deficiency in itself is not sufficient for the development of thrombocytopenia as shown in the ADAMTS13-deficient mouse in which platelet counts were normal and thrombi were not visualized in the kidneys." (PMID 21720563, 2011). "Decreased ADAMTS13 activity leads to a buildup of the ultra large vWF multimers along endothelial walls, resulting in platelet-rich microthrombi and the characteristic triad of thrombocytopenia, hemolytic anemia, and end-organ ischemia characterizing the disease." (PMID 40136473, 2025). "However, a complete loss of ADAMTS13 activity (i.e., <10%), thrombocytopenia, schistocytes are not common in COVID-19 infection." (PMID 35087853, 2021). "26.In critically ill children with COVID-19, thrombocytopenia-associated multiple organ failure (TAMOF: platelet counts of less than 100 × 109/l and two or more failing organs), and acquired ADAMTS-13 deficiency could indicate a thrombotic microangiopathic process." (PMID 32634818, 2020). "Patients with thrombocytopenia-associated multiple organ failure had lower ADAMTS-13 activity, non-survivors also had rich microvascular thromboses on autopsy, and there is data that intensive plasma exchange can replenish ADAMTS-13 activity and reverse organ failure in these children." (PMID 31434239, 2019). "Additionally, our study showed that excess VWF and ADAMTS13 deficiency are features of acute melioidosis, but are not the primary drivers of thrombocytopenia in melioidosis." (PMID 28296884, 2017). "Additionally, study results showed that excess VWF and ADAMTS13 deficiency are features of acute melioidosis, but are not the primary drivers of thrombocytopenia in melioidosis." (PMID 28296884, 2017).